PDK1 (pyruvate dehydrogenase kinase 1)
Diseases named in the same sentence as PDK1 in open-access papers (continued):
Sharing a sentence is not in itself a finding about the gene and the disease.
tumor (continued). "Understanding the specific mechanisms by which PDK1 regulates tumor metabolism and survival can pave the way for novel treatment strategies aimed at improving clinical outcomes for cancer patients." (PMID 40971960, 2025). "Lactylation enhances PDK1 activity, supporting glycolysis and tumor cell survival, while SHMT2 lactylation regulates one-carbon metabolism." (PMID 41458606, 2025). "In BC, PDK1 is genomically amplified and overexpressed, correlating with advanced tumor stage and poor prognosis 19,602,588." (PMID 40676293, 2025). "In contrast, our study demonstrated that pharmacological inhibition of PDK1 significantly reduced lung tumor burden in an experimental metastasis model and suppressed tumor growth in orthotopic and heterotopic xenograft mouse models in vivo." (PMID 40730548, 2025). "Further analysis found the higher the tumor grade, the higher PDK1 expression in ACC/CESC/PRAD patients (P < 0.05), with the detailed analysis results recorded in S8 Table." (PMID 40971960, 2025). "Previous research from our team has demonstrated that DCA reliably targets PDK1 and that inhibiting PDK1 is an effective strategy for inhibiting tumor growth by targeting glycolysis and reshaping the tumor microenvironment." (PMID 40873633, 2025). "It acts as a tumor suppressor in certain cancers through pathways like WNT/β‐catenin/PDK1, PGC1A/ERRA, and Melatonin/PGC1A/UCP1, regulating metabolism, signaling, and autophagy." (PMID 40119647, 2025). "This binding not only suppresses the enzymatic activity of JMJD2A but also interrupts the PDK1-Akt-mTOR signaling pathway, a vital cascade that is essential for tumor growth and survival." (PMID 41011214, 2025). "Pharmacological inhibition of PDK1 mirrored these genetic effects and repressed orthotopic tumor burden and pulmonary metastasis." (PMID 40730548, 2025). "Under HIF‐1α activation, glycolytic metabolism is enhanced through pyruvate dehydrogenase kinase 1 (PDK1) upregulation, boosting tumor cell proliferation." (PMID 40060193, 2025). "Mechanistically, these PROTACs reduce PDK1 expression and reverse the Warburg Effect in tumor cells, shifting glycolysis to OXPHOS." (PMID 40873633, 2025). "In some tumor cells, Lin28a and Lin28b regulated Pdk1 through let-7g to promote glycolysis and inhibit PDH activity." (PMID 39858120, 2025). "PDHC/PDK axis and PDK1 are significant targets for regulatingglucose metabolism and anti-tumor and activity." (PMID 40689201, 2025). "The current work found that the downstream targets of HIF-1α activity, metabolic markers Ang2, GLUT1, LDHA, and PDK1, which equip the tumor for survival and growth under hypoxic conditions, were also downregulated by anlotinib plus bevacizumab." (PMID 41041327, 2025). "Our data show that PDK1 is expressed under both normoxic and hypoxic conditions, with higher levels observed in hypoxic tumor tissue." (PMID 41465397, 2025). "Pyruvate dehydrogenase kinase 1 (PDK1) is a key modulator in the Warburg effect and is highly expressed in tumor cells." (PMID 40873633, 2025). "BC cell lines with mutations in the helical domain (Exon 9) have shown dependency on the 3-phosphoinositide-dependent-protein kinase 1 (PDK1) target for tumor growth." (PMID 39444377, 2024). "Together, these data demonstrate that the PRMT5-FUBP1- PDK1/SLC7A11 axis is enhanced in tumor cells." (PMID 39146021, 2024). "In cholangiocarcinoma, SIRT3 plays a tumor-suppressive role by downregulating the HIF1α/PDK1/PDHA1 pathway, leading to tumor regression." (PMID 39620228, 2024). "PPP2R2B is a regulatory subunit of a PP2A heterotrimeric complex, which has a role in recognizing dephosphorylated substrates, including cyclin E1 and PDK1, which participate in the cell cycle and tumor proliferation." (PMID 38976080, 2024). "PDK1 is a crucial glycolytic enzyme that is correlated to tumor growth, metastasis, and a poor prognosis." (PMID 39170516, 2024).
tumor (continued). "The angiogenesis assay showed that the supernatant from PDK1-expressing tumor cells had a more potent pro-angiogenic effect." (PMID 38560503, 2024). "Immunohistochemistry confirmed that entrectinib treatment reduced the expression of STAMBP, E2F1, PDK1 and Ki-67 expression in tumor tissues." (PMID 39242557, 2024). "BGN overexpression partially reverses the anti-tumor effects of PDK1 depletion on EOC cell malignant behaviors." (PMID 39578715, 2024). "Previous studies have shown that PDK1 can activate the PI3K/Akt/mTOR pathway to promote tumor proliferation and invasion; Additionally, phosphorylation of PDK1, an upstream regulator of C-Myc, activates PLK1-MYC signaling and promotes cancer proliferation." (PMID 38671369, 2024). "The accumulation of AKT in mitochondria can induce the phosphorylation of PDK1 at specific sites, reduce tumor cell death, maintain tumor cell proliferation, and induce EMT in the hypoxic environment." (PMID 38255198, 2024). "Future work is expected to build 3D tumor models to investigate the interaction between EOC cells and the microenvironment and the effects of the PDK1-BGN-NF κB axis on tumor progression." (PMID 39578715, 2024). "Previous studies highlighted that PDK1 promoted tumor development through several signal transduction mechanisms involved in senescence, metastatic tropism, and tumor maintenance." (PMID 38560503, 2024). "PDK1 acts as a critical regulator of aerobic glycolysis in tumor cells by phosphorylating the E1 subunit of pyruvate dehydrogenase (PDH) at Ser232, resulting in its inactivation." (PMID 39242557, 2024). "Disruption of the H3Y99sulf-H4R3me2a-TDRD3 axis can inhibit the expression and functions of hypoxia-inducible factor 1-alpha and PDK1, resulting in suppressed proliferation, tumor growth, and survival of HCC cells suffering hypoxia stress." (PMID 38311175, 2024). "ABCG1 is indicated to confer tumor stemness through activating the H19/HIF‐1α/PDK1 signaling pathway to induce rapid cancer cell growth and adaption to the condition of hypoxia and insufficient energy supply." (PMID 38896016, 2024). "Experimental evidence that pyruvate dehydrogenase kinase 1 (PDK1) and lysyl oxidase (LOX) genes associated with hypoxia is associated with tumor metastasis and survival, while decorin (DCN) can inhibit tumor." (PMID 38800967, 2024). "The involvement of PDK1 in aerobic glycolysis provides energy for tumor metastasis, highlighting its crucial role in immune response." (PMID 38577616, 2024). "This research elucidates the correlation between glycolysis and malignant tumor behavior while highlighting PDK subtypes—particularly PDK1 and PDK4—as potential therapeutic targets in CC." (PMID 38577616, 2024). "Currently, studies on the relationship between PDK1 and hypoxia regulation have focused on tumor- and cancer-cell-related studies." (PMID 39199957, 2024). "The Warburg effect is an important metabolic feature of tumour cells, and PDK-1 is a key enzyme in glycolysis, as it targets pyruvate dehydrogenase (PDH)." (PMID 36611209, 2023). "PDK2 and PDK3 protein expression in tumor cells correlated with lower patient overall survival, whereas PDK1 protein expression correlated with higher patient survival." (PMID 37147361, 2023). "Numerous studies have demonstrated the pivotal role of the PDK1/Akt pathway in promoting tumor formation and growth factor-mediated angiogenesis, thereby rendering the pathway an attractive target for therapeutic intervention." (PMID 38035024, 2023). "BX-795, functioning as a PDK-1/TBK-1 inhibitor, blocks PDK1/Akt signalling within tumour cells, thereby inhibiting their proliferation and inducing apoptosis." (PMID 38049741, 2023). "Formalin-fixed paraffin-embedded (FFPE) tumor blocks from EGFR mutant NSCLC tumors obtained prior to initiation of treatment or after tumor progression during treatment were stained with anti-PDK1 antibody for IHC analysis." (PMID 37169941, 2023).
tumor (continued). "PDK1 is regarded as a glycolysis gatekeeper and plays key roles in tumor growth and metastasis, macrophage polarization, and right ventricular fibrosis." (PMID 37935660, 2023). "Immunohistochemistry staining of PDK1 showed that the PDK1 expression in the SODD-KO xenograft tumor was remarkably lower than that of the WT ones." (PMID 37107587, 2023). "In tumor cells, Wnt signaling up-regulate glycolysis by directly targeting glycolytic enzymes such as pyruvate dehydrogenase kinase, isozyme 1 (PDK1)." (PMID 37089691, 2023). "To gain further insights into the contribution of the distinct PDK proteins in ccRCC, we evaluated by IHC the expression of PDK1-4 in tumor samples from a retrospective cohort of 96 ccRCC patients." (PMID 37147361, 2023). "Nonetheless, further investigations are required to explore the outcomes of PDK1 inhibition in the tumor microenvironment, including investigations in vascular endothelial cells." (PMID 38035024, 2023). "MiR-375 is downregulated in several cancers, where it acts as tumor-suppressor by targeting oncogenes like PDK1, and IGFR1 and by suppressing the PI3K/Akt pathway." (PMID 37869089, 2023). "IHC of PDK1 on the residual tumor tissues showed that the level of PDK1 expression was significantly lower in BX 795 treated tumors as compared with non-BX795 treated samples." (PMID 37169941, 2023). "Upregulation of PDK1 has been shown to circumvent endoplasmic reticulum stress-induced apoptosis in tumor cells." (PMID 37794585, 2023). "LncRNA DLX6-AS1 is overexpressed in GC and DLX6-AS1 knockdown inhibits tumor growth and aerobic glycolysis by targeting miR-4290 and 3-phosphoinositide-dependent protein kinase 1 (PDK1)." (PMID 36714260, 2023). "PDK1 increased expression in ccRCC tumor tissues has been documented previously both at mRNA and protein level." (PMID 37147361, 2023). "To further evaluate PDK1’s function in mediating MAPK4 tumor-promoting activity, we overexpressed PDK1 in the MAPK4-KO SUM159 and MDA-MB-231 cells." (PMID 37531320, 2023). "OnB demonstrate their capacity to effectively reprogram crucial genes associated with hypoxia and tumor suppression, such as MAT2A and PDK-1." (PMID 38063756, 2023). "Collectively, these data suggest that MAPK4 both PDK1-independently and -dependently regulates tumor cell response to PI3K blockade, and MAPK4 overexpression renders cancer cells at least partially resistant to PI3K and PDK1 co-blockade." (PMID 37531320, 2023). "Meanwhile, qPCR presented that PDK1 mRNA was substantially overexpressed in tumor tissues (P < 0.001)." (PMID 35264067, 2022). "Although JX06 is potent in inhibiting PDK1, it has limited solubility in water, fast blood clearance, making it hard to be targeted delivered to the tumor sites and finally enter the cancer cells." (PMID 35064767, 2022). "We found significantly smaller tumor sizes and weight in the miR-148a overexpression group as compared with miR-NC, and the PDK1 overexpression in miR-148a partially restored tumor growth." (PMID 35892859, 2022). "Myeloid-specific inactivation of PDK1 reprogrammed the metabolism of tumor-infiltrating macrophages and stimulated M1 macrophage polarization by inhibiting the mTOR pathway, while also retarding tumor growth and suppressing lung metastasis of BC model." (PMID 35159078, 2022). "Immune-related gene PDK1 is able to manipulate PD-L1 level in tumor tissue by mTOR signaling, and further affects the immune escape of tumor." (PMID 36245844, 2022). "The miR-375 gene is important for insulin secretion and glycogen synthase and acts as a tumor suppressor by downregulating numerous oncogenes, e.g. PDK1, JAK2, IGF1R, AEG-1, and suppressing the PI3K/Akt pathway." (PMID 35284957, 2022). "Taken together, these results suggest that PDK1 is involved in FOXM1‐mediated tumour growth in xenograft mice." (PMID 35656815, 2022). "Their findings indicated that the miR-128-3p/PDK1 axis is important in the metabolism and development of tumor cells." (PMID 36793341, 2022).
tumor (continued). "Consistent with the results observed in untransformed pPDH+ cells, sorted Pdk1-mCherry+ tumor cells displayed an increased ability to form new organoids, suggesting that this cell population is enriched in TICs." (PMID 35314684, 2022). "It has been demonstrated that pyruvate dehydrogenase kinase 1 (PDK1) and lysyl oxidase (LOX) were associated with chemoresistance, tumor metastasis, and poor survival." (PMID 36204682, 2022). "The tumor tissue immunohistochemistry (IHC) results showed lower PDK1 expression levels in the MDA-MB-231/miR-148a group than the miR-NC group." (PMID 35892859, 2022). "PDK1 has been reported to promote tumor cell migration and proliferation, and to regulate vessel growth in the colon tumor microenvironment." (PMID 35892859, 2022). "Depending on essential activities of PDK1 in tumor cells, analysts lately demonstrated that PDK1 acts as an appropriate therapeutic tool for anticancer and established multiple PDK1 blockers, including AR-12 and GSK233447, for the killing of cancerous cells." (PMID 36160435, 2022). "When we compared the expression level of MCT1 and PDK1 in our tumor groups, we found that both genes and proteins were higher or equally expressed in Wnt‐low compared with Wnt‐high tumors." (PMID 35904277, 2022). "This converting suppressed PIP3-dependent kinases (i.e., AKT, PDK1) that enhanced cell growth, protein synthesis, and cell cycling and migration and thereby inhibited tumor progression." (PMID 35421166, 2022). "For instance, Honokiol (HNK), a natural compound, inhibited the glycolysis of BC cells and indirectly blocked tumor growth by targeting HIF-1α/GLUT1/PDK1/HK2 pathway." (PMID 36532768, 2022). "In vivo, dicoumarol was able to reduce tumor growth, possibly by targeting the kinase activity of PDK1, which induced the apoptosis of tumor cells." (PMID 36575479, 2022). "Consistent findings were obtained in human invasive BC tissue microarray analysis, as a moderate to strong expression of PDK1 pSer241 was observed in 90% of all tumor specimens, in which 42% of evaluable specimens displayed strong expression (74/177 cores)." (PMID 35159078, 2022). "Signal-induced proliferation-associated 1 (SIPA1), a member of Rap1GAP family, promotes aerobic glycolysis by regulating the SIPA1/HIF-2α/PDK1 axis, leading to tumor invasion and metastasis in vivo." (PMID 36532768, 2022). "Next, we performed an in vivo experiment to investigate the effects of PDK1 modulation on tumor growth and metabolism: shPDK1 or shRNA tumor cells from OVCAR and OC316 cell lines were injected subcutaneously in SCID mice (n = 4 mice/group)." (PMID 33562444, 2021). "Our research showed that baicalin can suppress tumor progression by targeting the PDK1/AKT signaling pathway to inhibit EMT on NSCLC." (PMID 34868313, 2021). "Analysis of viable tumor areas uncovered increased proliferation as well as increased apoptosis in PDK1-silenced OVCAR3 tumors." (PMID 33562444, 2021). "It has been known that PDK1 is a key protein in PI3K signalling promoting the phosphorylation of T308 on AKT, which is closely associated with the development of tumours and plays an important role in multiple signalling for the tumorigenesis." (PMID 34431227, 2021). "We found that dysregulation of PDK1 resulting from ARNT depletion caused the cells to promote glucose uptake and mitochondrial activation, followed by ROS production and triggered tumor metastasis." (PMID 33446631, 2021). "PDK1 knockdown repressed EGF-induced tumor cell transformation, and the downregulation of PDK1 expression or inhibition of its activity significantly blocked EGF-enhanced cell migration and invasion." (PMID 33739396, 2021). "Our study confirmed that downregulation of PDK1 enhances tumor response to TKI treatment in oncogene-driven NSCLC cell lines." (PMID 34439291, 2021). "In vitro and in vivo study showed that PDK1 increased cell proliferation, migration, and invasion as well as tumor growth and metastasis." (PMID 33739396, 2021).
tumor (continued). "Our study also showed that down-regulation of PDK1 inhibits tumor cellular proliferation, migration, invasion, growth and anchorage-independent growth ability, and the difference was statistically significant." (PMID 33403023, 2021). "Lactate dehydrogenase A (LDHA) and pyruvate dehydrogenase kinase 1 (PDK1) are key players involved in anaerobic glycolysis and tumor progression." (PMID 33962616, 2021). "A rescue of PDK1 expression in Wnt-inhibited cancer cells rescues glycolysis as well as vessel growth in the tumor microenvironment." (PMID 33739396, 2021). "PDK1 is the pivotal protein in PI3K signalling activating the phosphorylation of AKT (T308), which is acknowledged to be closely associated with tumour progression." (PMID 34431227, 2021). "Cen and collaborators observed that AKT is frequently phosphorylated in ARMS and ERMS tissue microarray (TMA), indicating an activation of PDK-1/AKT pathway in this tumor, which plays a pivotal role in cell proliferation and survival." (PMID 34067464, 2021). "Subsequently, tumor tissue sections were prepared in each group, and the protein expression of PDK1, Ki67 and PD-L1 were detected by immunohistochemistry." (PMID 34394184, 2021). "There are convincing data demonstrating that increased PDK1 promotes tumor invasiveness and metastasis, while phosphorylation of AKT remains unaltered." (PMID 34789718, 2021). "At day 21, tumor volumes of shCTRL-silenced H1993 xenografts were significantly higher than those achieved by shPDK1-silenced H1993 xenografts indicating that downregulation of PDK1 reduces tumor growth." (PMID 34439291, 2021). "Our data are in line with many studies implicating the role of PDK1 in promoting tumour cell migration and invasion in various other cancers." (PMID 34298795, 2021). "PDK1 plays a significant role in aerobic glycolysis and regulates the biological behavior of tumor cells." (PMID 34926261, 2021). "High expression of PDK1 was closely correlated to tumor size, FIGO stage, extraovarian metastases status and distribution." (PMID 33403023, 2021). "At tumor harvest, we found by qPCR that PDK1 mRNA expression levels were still reduced in shPDK1 compared to control tumors, indicating that gene silencing effects were maintained." (PMID 33562444, 2021). "Euphol can enhance LC3-II levels directly in GBM cells or inhibits tumor invasion and migration through PDK1 modulation." (PMID 35300350, 2021). "Depletion of PDK1 impeded EGF-enhanced binding of HNSCC cells to endothelial cells as well as the metastatic seeding of tumor cells in lungs." (PMID 33739396, 2021). "In support of this notion, our earlier studies have shown that the KDM4A-E2F1 axis promotes tumor growth and metabolic adaptation through the regulation of the expression of cell-cycle related genes and PDK1/PDK332." (PMID 34335964, 2021). "Downregulation of miR-29c-3p promoted NPC cell migration and invasion by targeting TIAM1; miR-375-3p plays roles as a tumor suppressor by targeting oncogene PDK1, which promotes the proliferation, migration, and invasion of NPC cells." (PMID 34336826, 2021). "For instance, lncRNA-PDPK2P was shown to exhibit a higher level in HCC and accelerated invasion and tumor growth of HCC cells via PDK1/AKT/Caspase 3 pathway." (PMID 34513693, 2021). "The downregulation of ARNT and PDK1, accompanied by ROS production, indicates a high incidence of tumor metastasis." (PMID 33446631, 2021). "Conversely, the induction of SIRT3 was able to efficiently reduce tumor proliferation via an anti-Warburg effect mediated by the HIF1α/PDK1/PDHA1 pathway." (PMID 32138158, 2020). "Restoring the mitochondrial OXPHOS function by inhibiting glycolysis through targeting PDK1 has become a hot spot for tumor therapy." (PMID 31949499, 2020). "The relevance of the HIF1-α/Ku80/PDK1 pathway to alterations in metabolism of other cells in the tumour microenvironment will be important to determine." (PMID 33375613, 2020).